STAT6 (signal transducer and activator of transcription 6)
Diseases named in the same sentence as STAT6 in open-access papers (continued):
Sharing a sentence is not in itself a finding about the gene and the disease.
tumor (continued). "Immunohistochemically, the tumor cells were negative for CD34 but positive for STAT6 and vimentin." (PMID 31020464, 2019). "Taken together, these data showed that IL-4-activated Stat6 directly suppresses TRIM24 gene expression during macrophage M2 polarization, which may in turn contribute to immunosuppressive profiles in the context of the tumor microenvironment." (PMID 31554795, 2019). "The inflammatory milieu of the tumor microenvironment affects different intracellular master regulators of TAMs such as Signal Transducer and Activator of Transcription factors (STAT3 and STAT6 for M2, STAT1 for M1 polarization), the nuclear factor-κB (NF-κB), RORC1, and HIF-1." (PMID 28197019, 2017). "Therefore, STAT6 could be considered a highly sensitive and nearly ideal marker for the differentiation of SFT from other neoplasms." (PMID 28494796, 2017). "Moreover, immunohistochemical analyses of STAT6 revealed a diffuse nuclear expression in almost all SFTs, but not in other tumours." (PMID 28494796, 2017). "Only one histologically conventional, pleura‐based tumor was STAT6‐negative." (PMID 26686340, 2016). "There does not appear to be a correlation between STAT6 expression and tumor grade, suggesting STAT6 may play a role early in the process of transformation." (PMID 21595984, 2011). "Interestingly, the tumor bearing condition did not suppress miR-17-5p expression by CD4+ T cells in STAT6-/- mice." (PMID 20167088, 2010). "However, due to the inversion of STAT6 in SFT, the NAB2-STAT6 fusion gene creates a sequence that increases the distance between the probes or may even result in the deletion of a yellow signal in the tumor cell." (PMID 39120790, 2024). "However, monotherapy using free STAT6–ASO was not effective in inhibiting tumor growth." (PMID 39272802, 2024). "Therefore, novel ASOs could be designed to target the 3′-UTR of STAT6, which could in theory suppress the expression levels of both wild type STAT6 and all known NAB2–STAT6 fusion transcripts, especially if a SFT-tumor-specific ASO delivery method is developed." (PMID 37370737, 2023). "Finally, an overexpression of this miR leads to a reduced JAK1, STAT6, and AKT phosphorylation and IL-4-induced migration and invasion; this, together with data from the literature, leads to the conclusion that miR-494-5p is an early tumor and initial metastasis suppressor in CRC." (PMID 38201452, 2023). "Macrophage polarization may be reprogrammed to tumor cell killing by treatment with tyrosine kinase inhibitors sunitinib and sorafenib, or fenretinide [4-hydroxy (phenyl) retinamide], which inhibit STAT3 or STAT6 in macrophages, thereby blocking IL-10 secretion." (PMID 34831167, 2021). "Furthermore, under hypoxic conditions, the decrease of STAT6 could activate the mTOR signaling pathway, promote hypoxia-inducible factor-1 (HIF-1α) protein synthesis, and eventually enhance the viability and anti-apoptotic ability of tumor cells." (PMID 33013320, 2020). "Conversely, in a cohort of patients that had been treated with radiotherapy alone, STAT6 expression showed a clear trend towards a poor clinical outcome, which could be explained by the immune-evasive potential of STAT6-expressing tumor cells, if not attacked by platinum." (PMID 22611421, 2012). "Importantly, the relative resistance of the STAT6 -/- mice to xenograft tumors suggests that the enhanced anti-tumor immunity observed in these animals is a not a consequence of STAT6 depletion in the tumor cells, but rather results from its loss within the host tumor microenvironment." (PMID 21595984, 2011). "Furthermore, STAT6--a signal transducer downstream in the IL-13 receptor signaling pathway--is phosphorylated, suggesting the IL-13 from infiltrating CD4+ T cells in the tumor microenvironment may contribute to tumor development." (PMID 21281484, 2011). "Tumor cells were negative for CD34, TFE3, STAT6, ALK1, PAX8, AE1/3, and other epithelial, neural, and myogenic markers." (PMID 40948436, 2026).
tumor (continued). "Although direct therapeutic strategies targeting STAT6 in PTC are not yet fully mature, its key role in the tumor immune microenvironment offers broad prospects for future therapeutic exploration." (PMID 40230479, 2025). "Immunohistochemically, the tumor was positive for CD34, vimentin, and STAT6, and negative for α‐SMA, S100, c‐kit, and desmin." (PMID 40336741, 2025). "Tumor cells express diffuse positive expression for smooth muscle actin and β-catenin, while negative reaction for CD34 and STAT6." (PMID 41226013, 2025). "Immunohistochemically, the tumor was positive for alpha-smooth muscle actin, but negative for CD34, desmin, keratin 18, S-100 protein, melan A, c-kit, and STAT6." (PMID 38805072, 2024). "Tumor cells were positive to vimentin and CD99, but negative to S-100, SMA, HHF-35, desmin, CD31, CD34, STAT-6 and pan-cytokeratin (AE1/AE3)." (PMID 39462411, 2024). "Tumor cells were positive for CD34, signal transducer and activator of transcription 6 (STAT6), CD99 and B-cell lymphoma 2 (Bcl-2) but negative for smooth muscle actin (SMA), desmin and S100." (PMID 39678506, 2024). "Immunohistochemistry demonstrated the tumor cells to be positive for CD34, CD99, STAT6, and BCL-2, while negative for S-100, CD45, P-CK, CD56 (focally positive), Sy, GFAP, SALL4, OCT3/4, and Desmin." (PMID 39175476, 2024). "Tumor cells in case 3 of our study were positive to vimentin and CD99 but they were negative to S-100, desmin, HHF-35, SMA, CD31, CD34, STAT-6 and pan-cytokeratin (AE1/AE3)." (PMID 39462411, 2024). "Immunohistochemically, the tumor cells were positive for CD34 and STAT6, and negative for smooth muscle actin, desmin, S100-protein, and epithelial membrane antigens." (PMID 37315497, 2023). "The tumor cells expressed SATB2, Bcl-2, TLE1, SMARCB1, but not CK, EMA, CD34, SMA, Desmin, S-100, CD99, STAT6, MyoD1, Myogenin, and Ki-67 LI is about 10%." (PMID 37361584, 2023). "Taken together, our data suggest that nonmutant stromal fibroblasts induce mutant desmoid tumor cell proliferation via secreting soluble factors, including PTX3 and STAT6 activation." (PMID 37377751, 2023). "On the contrary, negative correlations existed in only several tumor types, such as BLCA and STAT6, GBM and STAT5B, and SARC and STAT5B." (PMID 36968603, 2023). "Normally, BSNS tumours show immunoreactivity for S100, SMA and sometimes desmin but demonstrate no reaction with CD34, STAT6, EMA and myogenin, which was also included in the report of all three cases presented." (PMID 38027532, 2023). "The tumor cells showed immunopositivity for CD34, STAT-6, and no expression of CD99, AML, S-100, and Ki-67." (PMID 36426115, 2022). "Immunohistochemically, the tumor cells were positive for CD117, vimentin, CD56 and NSE and focally expressed desmin; the cells were negative for myogenin, S-100, SYN, INSM1, CD34, STAT6, INI-1, Brachyury, ERG, TLE1, AE1/AE3, WT-1, CD99 and SMA." (PMID 35488288, 2022). "Tumor cells showed immunopositivity for CD34 and STAT-6 and no expression of CD99, AML, S-100, and Ki-67." (PMID 36426115, 2022). "Immunohistochemical staining indicated the tumour was positive for CD34, STAT6, vimentin and bcl-2, but negative for cytokeratins, D2-40 and S-100." (PMID 33623662, 2021). "In contrast, the tumor cells were nonreactive for SF-1, inhibin alpha, desmin, HHF35, HMB45, Melan A, MITF, c-kit, DOG1, cytokeratin AE1/AE3, h-caldesmon, STAT6, CD68, MDM2, CDK4, c17, DHEAST, 3BHSD, CD31, Factor 8, and ERG." (PMID 34797454, 2021). "The tumor cells were negative for CD117, DOG1, CD34, S100, β-catenin, STAT-6, and ALK that played important roles in differential diagnosis." (PMID 34516510, 2021). "Tumor cells were nonreactive for SF-1, inhibin alpha, desmin, HHF35, HMB45, Melan A, MITF, c-kit, DOG1, cytokeratin AE1/AE3, h-caldesmon, STAT6, CD68, MDM2, CDK4, c17, DHEAST, 3BHSD, CD31, Factor 8, and ERG." (PMID 34797454, 2021).
tumor (continued). "Tumor cells showed negative staining for the following markers: CD117 (n = 4), CD34 (n = 3), DOG-1 (n = 4), STAT6 (n = 2), EMA (n = 2), Desmin (n = 3), and SMA (n = 3)." (PMID 33588954, 2021). "IHC analyses revealed that the tumor cells were positive for EMA and CD34 and negative for claudin-1, GLUT1, S100 protein, MUC4, STAT6, SMA, HMB45 and P16." (PMID 34592995, 2021). "The tumor cells were robustly and diffusely positive for Trk, S100-protein, CD34, and nestin, but negative for CD56, SMA, desmin, myogenin, STAT6, EMA, CK, CD1a, CD21, CD35, CD43, WT-1(c-terminal), MelanA, HMB45, BRAF, and ALK." (PMID 32957984, 2020). "The tumor cells were positive for Trk and SMA, but negative for S100, CD34, ALK, CD10, desmin, myogenin, CD99, CD56, CK, EMA, and STAT6." (PMID 32957984, 2020). "Immunohistochemistry demonstrated that the tumor cells were positive for CD34, STAT6, vimentin, and Bcl-2, and negative for α-SMA, S100, and EMA." (PMID 31687030, 2019). "Immunohistochemically, the tumor cells were diffusely positive for CD34, STAT-6 and FLI-1, but negative for pan-cytokeratin, CAM5.2, p63, S100 protein, CD31, SMA, and calponin." (PMID 30777087, 2019). "Histological evaluation of the septated, cystic mass revealed tumour cells forming an irregular patternless pattern; immunohistochemically, the cells tested positive for vimentin, CD34, CD99 and STAT6 but negative for keratin (AE1-AE3), CD31 and S100." (PMID 28865431, 2017). "The tumor is not reactive to pancytokeratin, CD31, STAT6, S100, or SOX10." (PMID 41246587, 2025). "Histopathology revealed a cellular tumor comprising tightly packed round to fusiform cells arranged around blood vessels with intervening thick collagen, positive for CD99, vimentin, BCL2, CD34, and STAT6 and negative for EMA, CK AE1/AE3, S100, TLE1, and SMA." (PMID 38606238, 2024). "Tumor cells express desmin and CD34 but are negative for CD99, Bcl-2, and STAT6." (PMID 39206171, 2024). "The neoplasm showed positivity for Smooth Muscle Actin, MDM2 (focally), and pan-TRK, while Caldesmon, CD31, CK AE1/AE3, Desmin, ERG, S100, SATB2, STAT6, H3F3A (G34V), H3F3A (G34W), H3F3A (G34R), SS18-SSX, SSX, STAT6, and CD34 were negative." (PMID 37876963, 2023). "The tumor cells were negative for AE1/3, Cam5.2, CKIT, DOG1, CD99, SOX10, S100, HMB45, MelanA, Syn, CgA, Trypsin, Desmin, SMA, Caldesmon, collagen type 4, Laminin, Inhibin, Calretinin, STAT6, CD34, ERG, WT1, ER, PR, and SALL4." (PMID 36928336, 2023). "Q11 does not directly affect tumor cells but blocks the tumor‐promoting effect of microglia/macrophage (M/Mφ) in the tumor microenvironment through PPARγ‐mediated activation of the STAT‐1 and NF‐κB pathways and inhibition of the STAT‐3 and STAT‐6 pathways." (PMID 37283464, 2023). "Histologically, a cellular tumor comprising malignant oval to spindle cells with necrosis was observed, which was positive for Bcl-2, CD99, and FLI-1, but negative for pan-cytokeratin, STAT6, and CD34." (PMID 36033527, 2022). "The tumor was positive for CD117, Vim, CD56 and NSE and showed focal expression of desmin but was negative for myogenin, S-100, SYN, INSM1, CD34, STAT6, INI-1, Brachyury, ERG, TLE1, AE1/AE3, WT-1, CD99 and SMA." (PMID 35488288, 2022). "However, the tumor cells were negative for S-100 protein, SMA, desmin, myogenin, CD99, Fli-1, CD56, STAT6, CK and EMA." (PMID 32957984, 2020). "By immunohistochemistry, tumor cells demonstrated strong nuclear cyclin D1 expression and multifocal smooth muscle actin staining but were negative for MUC4, ERG, CD34, S-100 protein, desmin, STAT6, CD45, MDM2, CDK4, ALK, and ROS1." (PMID 32461620, 2020).
tumor (continued). "The tumor cells were diffusely positive for CD34, STAT-6 and FLI-1, and negative for pan-cytokeratin, CAM5.2, p63, S100 protein, CD31, SMA, and calponin.ERG and Ki67 immunostaining showed an accentuated nuclear staining pattern in the central dedifferentiated area." (PMID 30777087, 2019). "Tumor cells exhibit no strong diffuse staining for CD34 and are basically negative for AE1/AE3, Bcl-2, CD34, CD99, CD117, Factor VIIIR Ag, S-100 protein, and STAT6." (PMID 30206803, 2019). "Additionally, the tumor was negative for most immunohistochemical markers (CKAE1/AE3, p63, CD23, CD21, MUC4, NUT, CDK4, Pan-TRK, STAT6, SS18, MDM2, Desmin, S100, ERG, TLE1, Fli) and showed only weak and most probably unspecific expression of CD99, CD56, and CD34." (PMID 39519042, 2024). "(Immunohistochemical stains showed that the tumor cells were positive for desmin and TFE3, while negative for pancytokeratin, CAM5.2, EMA, chromogranin, synaptophysin, NSE, CD45, SMA, HHF35, myogenin, CD117, DOG1, MUC4, S100, SOX10, HMB45, Melan-A, CD31, ERG, TLE1, STAT6, and Cathepsin-K)." (PMID 35001360, 2022). "Similarly, no p-STAT6 and p-JAK2 staining appeared in the primary tumor cells." (PMID 34090412, 2021). "Tumor cells may show positive expression for CD34 and ASMA but STAT6 is negative." (PMID 33879215, 2021). "In addition, STAT6 is a reliable marker for SFT and has not been described in the other tumours." (PMID 26358059, 2015).
cancer (138 papers, 2009 to 2025). A tumor composed of atypical neoplastic, often pleomorphic cells that invade other tissues. "The transcription factors STAT3 and STAT6 regulate cell functions like growth, differentiation, and immune responses, with aberrations in their activation linked to cancer, autoimmunity, and inflammation." (PMID 40309479, 2025). "Members of the STAT family, in particular STAT6, are shown to be associated with the initiation, metastasis, progression, survival, and treatment resistance of human cancer." (PMID 38419894, 2024). "The enhanced expression of cytokines and their receptors mainly result in the aberrant regulation of JAK1/2, STAT1, STAT3, STAT5, and STAT6, causing inflammation and cancer development, cancer recurrence, and decreased overall survival." (PMID 38094755, 2023). "Previous studies have shown that STAT6 is associated with the tumorigenesis, immunosuppression, proliferation, metastasis and poor prognosis of human cancers." (PMID 35269804, 2022). "In fact, STAT6 seems to play a significant role in transcription and inflammation, processes linked to cancer development and progression." (PMID 34299133, 2021). "The cancer cells increase the number of CD11b+ cells, while STAT6 deficiency suppresses the formation of CD11b+ cells." (PMID 31798581, 2019). "The results show that both the volume and weight of tumors from STAT6−/− CD11b+ cells are less than those from STAT6+/+ CD11b+ cells, suggesting that CD11b+ cells derived from STAT6−/− mice are associated with the reduction of cancer development." (PMID 31798581, 2019). "Extensive studies have revealed that the dysregulation of STAT6 is linked to the pathological features of virus-associated cancers." (PMID 30532138, 2018). "Expression of p21 is associated with apoptotic cell death and growth arrest of cancer cells in conjunction with STAT6 activity." (PMID 26993600, 2016). "Like STAT2 and STAT4, the role of STAT6 remains largely unknown, though there is some evidence that STAT6 is associated with supporting the cancer stem cell niche in OvCa." (PMID 37173951, 2023). "Moreover, due to the deficiency in our understanding of STAT1, STAT2, STAT4, and STAT6 in cancer, selective inhibitors also remain elusive." (PMID 37173951, 2023). "STAT6 is associated with cancer cell proliferation, an increased malignancy and poor prognosis." (PMID 31075146, 2019). "Deficiency of STAT6 downregulates CD11b expression in nearby myeloid cells, thereby inhibiting further myeloid differentiation, especially to macrophages, and suppresses the initiation and promotion of cancer cells." (PMID 31798581, 2019). "Aberrations in STAT6-mediated signaling are linked to the development of multiple cancer types." (PMID 30532138, 2018). "Analyses of potential correlations between genetic alterations of Stat6, CDK4 and p27 expression could be decisive in clarifying the role of Stat6 in familial predisposition to certain cancers and/or failure of hormonal therapy." (PMID 24401087, 2014). "Beyond this case study, several evidence involve STAT6-driven type 2 polarization of immunity in cancer." (PMID 41409600, 2025). "Beyond immune reaction, STAT6 can orchestrate cancer cell proliferation and apoptosis, cell adhesion and invasiveness, chromatin compaction and DNA damage response." (PMID 39936166, 2025). "Accumulating evidence indicates that aberrant activation of STAT5 and STAT6 signaling promotes the expression of target genes, increasing cell proliferation, survival, and metastasis in various cancers." (PMID 40105652, 2025). "The literature indicates that STAT6 plays important roles in regulating cell viability and inducing apoptosis in various cancer types." (PMID 40733498, 2025). "STAT6, a signal transducer and activator of transcription 6, has shown promise as a powerful target for anti-cancer medications." (PMID 38554148, 2024).